OTOGL (otogelin like)
Synonyms: C12orf64; FLJ90579; DFNB84B
Tractability: Antibody: UniProt places it where antibodies can reach, with high confidence; UniProt predicts a signal peptide or a membrane-spanning region; its Gene Ontology location is reachable by antibodies, with medium confidence.
Gene: Protein-coding gene on chromosome 12 (80,099,537 to 80,380,880, forward strand). Ensembl gene ENSG00000165899.
Subcellular location: Secreted
Subcellular location (Human Protein Atlas): Cytosol; Predicted to be secreted
Pathways (Reactome):
Sensory Perception: Sensory processing of sound by outer hair cells of the cochlea
Gene Ontology:
Molecular function: protein binding; extracellular matrix structural constituent; alpha-L-arabinofuranosidase activity
Biological process: L-arabinose metabolic process
Cellular component: extracellular matrix; extracellular region
Genetic constraint (gnomAD): Loss-of-function variants: 201 observed, 211.35 expected, observed/expected ratio (o/e) 0.95, 90% interval 0.85 to 1.07. The upper end of that interval is the gene's LOEUF score, 1.07, which puts it in group 4 of 6, group 1 being the genes least tolerant of losing a copy. Missense variants: 2,415 observed, 2,274.4 expected, observed/expected ratio (o/e) 1.06, 90% interval 1.03 to 1.1. Synonymous variants: 816 observed, 762.24 expected, observed/expected ratio (o/e) 1.07, 90% interval 1.01 to 1.13.
Gene-disease validity (ClinGen):
ClinGen rates the evidence that OTOGL causes each of these diseases.
nonsyndromic genetic hearing loss (autosomal recessive): Definitive. A disease characterized by hearing loss that is not part of a larger syndrome.
Homologues: Orthologues: chimpanzee OTOGL (99% identical), macaque OTOGL (97% identical), dog OTOGL (92% identical), rabbit OTOGL (91% identical), pig OTOGL (88% identical), mouse Otogl (86% identical), rat Otogl (86% identical), guinea pig OTOGL (83% identical), tropical clawed frog otogl2 (62% identical), zebrafish otogl (53% identical). Paralogues in human: OTOG (39% identical), VWF (25% identical), MUC5AC (24% identical), MUC5B (23% identical), FCGBP (19% identical), MUC19 (16% identical), MUC6 (16% identical), MUC2 (15% identical), ZAN (15% identical), TECTA (15% identical), KCP (12% identical), CRIM1 (9% identical), and 7 more.
Diseases named in the same sentence as OTOGL in open-access papers:
OTOGL is named in the same sentence as 11 diseases in open-access papers, as found by Europe PMC text mining. Sharing a sentence is not in itself a finding about the gene and the disease. The quoted sentences say what the papers report.
hearing loss (8 papers, 2015 to 2025). "In this study, we aim to enhance our comprehension of the phenotypes of hearing loss caused by OTOGL variants." (PMID 40004452, 2025). "OTOGL gene variants are a rare cause of hearing loss such as DFNB84B, a mild-to-moderate sensorineural hearing loss presenting in early childhood with autosomal recessive inheritance." (PMID 40004452, 2025). "OTOGL mutations have been found to be associated with hearing loss." (PMID 37107573, 2023). "These high priority genes, including MPHOSPH8, MYO18A, TRIOBP, OTOGL, TNC, and MYO6, were previously implicated in hearing loss, balance, and cochlear function, and were significantly enriched in common variant studies of hearing loss." (PMID 38943082, 2024). "Mutations of the genes encoding OTOG (otogelin, DFNB18B), OTOGL (otogelin-like, DFNB84B), and TECTA (α-tectorin, DFNA8/12, DFNB21) have been associated with hearing loss in humans, with occasional reports of vestibular hyporeflexia or vertigo in patients with OTOG or TECTA defects." (PMID 35444606, 2022). "Although rare variants in TECTA, OTOG, and OTOGL have been associated with hearing loss, none of the variants identified in the current meta-analysis associate with hearing loss, identified by ICD-10 codes H90 and H91, nor any rare variants in the six GWAS candidate genes." (PMID 34620984, 2021).
deafness (5 papers, 2014 to 2024). An inherited or acquired condition characterized by the complete loss of the ability to hear from one or both ears. "Although human OTOG mutations have been linked to deafness, the biological function of OTOGL in male germ cell development remains enigmatic." (PMID 34174893, 2021). "Segdups, defined as regions with > 95% homology, are features that are causally implicated in recurrent CNVs mediated by NAHR and were identified in seven deafness genes: TSPEAR (4 segdups), OTOA, STRC, MYO3A, ESPN, OTOGL, CACNA1D." (PMID 24963352, 2014).
Vertigo (4 papers, 2021 to 2024). An abnormal sensation of spinning while the body is actually stationary. "Variants in OTOG and otogelin like (OTOGL), otopetrin 1 (OTOP1), tectorin α (TECTA), zinc finger protein 91 (ZNF91), and armadillo repeat containing 9 (ARMC9) were associated with vertigo in a recent genome-wide meta-analysis." (PMID 35741759, 2022). "Here, we report an association between vertigo in humans and a missense mutation in OTOG (Thr375Ser, rs7130190-T, EAF = 16.2%, P = 9.0 × 10−14, OR = 1.08) and OTOGL (Gln1102His, rs10862089-T, EAF = 7.50%, P = 1.2 × 10−13, OR = 1.11)." (PMID 34620984, 2021). "The vertigo association with the sequence variants at ZNF91, OTOP1, and OTOGL appears to be driven by their risk of BPPV." (PMID 34620984, 2021).
auditory neuropathy (1 paper, 2025). A hearing disorder characterized by impaired transmission of signals through the auditory nerve, resulting in mild to severe hearing loss and poor speech perception. "Studies of OTOGL+/− humans may therefore be invaluable to unveil new possibilities for identifying a specific auditory circuit involved in sound hypersensitivity, and to unravel the links between auditory neuropathy and auditory hyperexcitability." (PMID 39965080, 2025).
Azoospermia (1 paper, 2021). Absence of any measurable level of sperm,whereby spermatozoa cannot be observed even after centrifugation of the semen pellet. "In screening 336 patients with non-obstructive azoospermia (NOA), OTOGL displays the high mutant ratio (13.99 %)." (PMID 34174893, 2021).
sensorineural hearing loss (1 paper, 2018). "Pathogenic mutations in OTOGL are associated with sensorineural hearing loss." (PMID 29320387, 2018).
OTOGL also shares sentences with these, for which no sentence is quoted: Hearing impairment (2 papers); autosomal recessive deafness (1); hearing (1); hearing disorder (1); male infertility (1).